LINC01226 (long independently transcribed non-coding RNA 1226)
Synonyms: SEELA2
Gene: Long non-coding RNA gene on chromosome 1 (31,506,209 to 31,583,306, forward strand). Ensembl gene ENSG00000284543.
Diseases named in the same sentence as LINC01226 in open-access papers:
LINC01226 is named in the same sentence as 1 disease in open-access papers, as found by Europe PMC text mining. Sharing a sentence is not in itself a finding about the gene and the disease.
LINC01226 shares sentences with these, for which no sentence is quoted: leukemia (1 paper).